RNU6-374P (RNA, U6 small nuclear 374, pseudogene)
Gene: Small nuclear RNA gene on chromosome 5 (25,701,217 to 25,701,324, reverse strand). Ensembl gene ENSG00000201016.
Homologues: Orthologues: chimpanzee U6 (96% identical), macaque U6 (78% identical), pig U6 (76% identical), guinea pig U6 (67% identical), dog U6 (65% identical), rat LOC120094405 (65% identical), mouse Gm24399 (52% identical). Paralogues in human: RNU6-348P (86% identical), RNU6-1145P (85% identical), RNU6-19P (85% identical), RNU6-393P (85% identical), RNU6-41P (85% identical), RNU6-44P (85% identical), RNU6-737P (85% identical), RNU6-1181P (84% identical), RNU6-12P (84% identical), RNU6-1316P (84% identical), RNU6-13P (84% identical), RNU6-166P (84% identical), and 1285 more.